GLP1R (glucagon like peptide 1 receptor)
Diseases named in the same sentence as GLP1R in open-access papers (continued):
Sharing a sentence is not in itself a finding about the gene and the disease.
Hyperglycemia (continued). "A previous study revealed that a shift in G protein signaling of GLP-1R from Gs to Gq allows GLP-1R agonists to stimulate insulin secretion in β-cells exposed to chronic hyperglycemia and subsequent prolonged membrane depolarization." (PMID 38376482, 2024). "This is in line with hyperglycaemia‐induced reduction of GLP‐1R expression and impaired cAMP‐mediated effects in β‐cells." (PMID 33611845, 2024). "It was reported that hyperglycemia and persistent depolarization of β-cells led to GLP-1R’s signaling switch from Gs to Gq, whereas GIPR continued to rely on Gs." (PMID 38376482, 2024). "GLP-1R activation reduces hyperglycaemia and mediates vascular relaxation and NHE-3 inactivation, leading to decreased proximal sodium reabsorption and natriuresis, thus protecting against hypertension and glomerular hyperfiltration." (PMID 39526061, 2024). "The expression pattern of GLP-1R in the OA group was similar to hyperglycemia group but stained in a darker color." (PMID 37520251, 2023). "STZ induced hyperglycemia dramatically reduced the glucagon-like peptide-1 receptor (GLP-1R) positive cells in islets, all the three treatments significantly increased the pancreatic GLP-1R positive cell number." (PMID 37520251, 2023). "We report that GLP1R blockade raises fasting glucose and impairs the islet response to hyperglycemia." (PMID 37751301, 2023). "Mendelian randomisation studies support a causal role of genetically driven hyperglycaemia in atherosclerotic CVD (ASCVD) and show that glucose-lowering variants of the GLP-1 receptor (GLP-1R) gene, GLP1R, confer protection against heart disease." (PMID 37542009, 2023). "EtOH+OA group shows a higher β-cell ratio than EtOH, and a greater α-cell ratio than OA, at the same time, the GLP-1R positive cell number is significantly bigger than the hyperglycemia group." (PMID 37520251, 2023). "In comparison with hyperglycemia group, OA, EtOH or OA+EtOH treatment increased the number of positive GLP-1R cells as well as GLP-1R positive cell to total islet cell ratio." (PMID 37520251, 2023). "On the other hand, there is active consideration for the use of glucagon-like peptide 1 receptor agonists (exenatide, liraglutide, dulaglutide) in the setting of calcineurin inhibition or tacrolimus-related hyperglycemia." (PMID 37759585, 2023). "In the islet of hyperglycemia group, GLP-1R was stained with brown color and randomly distributed in some cell soma." (PMID 37520251, 2023). "Hyperglycemia leads also to decreased expression of GLP-1R in streptozotocin-treated mice and in the human RPE cell line ARPE-19." (PMID 36293281, 2022). "Liraglutide, on the other hand, has been shown to reduce hyperglycemia in type 1 diabetic rats by activating the GLP-1R in the adrenal gland." (PMID 35890201, 2022). "Modest data on the effects of central GLP-1R inhibition indicate that during hyperglycemia, such a treatment leads to increased peripheral glucose utilization and insulin sensitization in mice." (PMID 35008973, 2022). "Although more research is required, the affinity of GLP-1R in the adrenal gland raised by hyperglycemia seems possible." (PMID 35890201, 2022). "Regulated nuclear factor kappa-b NF-kB activation and subsequent inflammatory response in mesangial cells are involved in the hyperglycemia-induced downregulation of GLP-1R." (PMID 35392872, 2022). "The activation of this pro-inflammatory protein complex is induced by hyperglycemia and attenuates the therapeutic effects of the GLP-1R agonist by its downregulation." (PMID 34501404, 2021). "In vitro study unravels that hyperglycemia impairs glucagon-like peptide-1 receptor (GLP-1R) expression in HBZY-1 rat mesangial cell line, paralleled with NF-κB activation and increased MCP-1 protein levels." (PMID 33584319, 2021). "In streptozotocin-induced hyperglycemic mice model, we demonstrated that PGLP-1-VP can act as a GLP-1R agonist to improve hyperglycemia and increase insulin sensitivity." (PMID 33574570, 2021).
Hyperglycemia (continued). "Updates on the cardioprotective roles of the new classes of hyperglycemia-targeting therapies, the sodium glucose transport protein 2 inhibitors and the agonists of the glucagon-like peptide 1 receptor system, are reviewed." (PMID 34081211, 2021). "GLP-1 treatment has been reported to alleviate diabetic retinopathy by inhibiting hyperglycemia-provoked autophagy in the retina of T2D rats mediated through the restoration of GLP-1R expression and HDAC6 inhibition." (PMID 34071497, 2021). "Decreased TCF7L2 protein levels in T2DM correlated with the downregulation of GIP and GLP-1 receptors (GIP-R and GLP-1R), and impaired β-cell function, lead to fasting and postprandial hyperglycaemia." (PMID 32090124, 2020). "The tri-agonist also protected these mice from fasting hyperglycaemia and to a better degree than the GLP-1R/GIPR co-agonist." (PMID 32269764, 2020). "The present study demonstrated that liraglutide activates GLP-1R to reduce hyperglycemia in rats with STZ-induced type-1 diabetes." (PMID 33233692, 2020). "Post-transplant DM is due to an impaired β-cell function and glucose-induced glucagon suppression during hyperglycemia, which can be reversed by GLP-1R." (PMID 31261624, 2019). "There are two classes of incretin-based therapies for the management of hyperglycemia in T2DM: GLP-1R agonists and DPP-4 inhibitors." (PMID 31159279, 2019). "Based on these reports, it is necessary to develop new approaches to safely treat hyperglycemia as well as to preserve endogenous GLP-1R." (PMID 30866463, 2019). "Incretin mimetics present other favorable properties such as a low hypoglycaemia risk, the ability to address postprandial hyperglycemia (DPP-4 inhibitors and short-acting GLP-1R agonists), and potential for weight reduction (GLP-1R agonists; Neumiller, 2015)." (PMID 28111551, 2016). "It was demonstrated that hyperglycemia itself contributes to downregulation of GLP-1R expression in islets of rat pancreas in vivo and in vitro and this effect is more prominent after long-term (4 weeks) hyperglycemia in vivo." (PMID 25893200, 2015). "Integrated over the total five week study period the GLP-1R agonist reduced hyperglycemia in random fed mice by 30%." (PMID 24423471, 2014). "The main finding in this paper is that once daily injections with the DPP-4-resistant GLP-1R agonist liraglutide delay the development of hyperglycemia and promote beta-cell function in a mouse model of GC-induced metabolic syndrome." (PMID 24423471, 2014). "An understanding of the molecular pathways involved in insulin secretion is useful in explaining such clinical observations as the ability of GLP-1R agonists to reduce hyperglycaemia with a low likelihood of hypoglycaemia." (PMID 22776039, 2013). "The 24-week duration of hyperglycemia in untreated diabetic rats resulted in decrease of GLP-1R staining." (PMID 24089613, 2013). "In rat islets, hyperglycemia has also been shown to decrease gene expression of the GLP-1R by approximately 50%." (PMID 22937169, 2012). "Notably, rosmarinic acid and resveratrol have been shown to alleviate hyperglycemia in diabetic mouse models, partly through activation of GLP-1R-mediated signaling pathways." (PMID 41373699, 2025). "Considering the patient’s persistent hyperglycemia and the maternal history of thyroid cancer, which made Glucagon-Like Peptide-1 receptor agonists (GLP1-RA) less suitable, empagliflozin therapy was initiated at a dose of 10 mg daily, while maintaining metformin therapy." (PMID 41001667, 2025). "Hence, incretin-based drug development to control diabetic hyperglycaemia has been biased toward targeting the GLP-1 receptor (GLP-1R)." (PMID 39200816, 2024). "These latter findings suggest that: (i) DNA methylation changes might also play a significant role in our setting; (ii) GLP-1R agonists could be useful in preventing hyperglycemia-induced trained immunity and monocyte inflammation." (PMID 38553774, 2024).
Hyperglycemia (continued). "Based on a previous report documenting GLP-1R’s Gs to Gq signaling switch under hyperglycemic conditions, we hypothesized that ER stress under hyperglycemia or other metabolic stress under T2D might elicit such a signaling shift in β-cells." (PMID 38376482, 2024). "However, little is known about GLP-1R’s unique signaling switch to Gq other than the fact that it is triggered by hyperglycemia and β-cell depolarization." (PMID 38376482, 2024). "It is therefore possible that activation of JNK kinases downstream of GLP‐1R action might lead to differential signalling effects than those triggered by chronic hyperglycaemia." (PMID 37039251, 2023). "Moreover, novel GLP-1R/GIPR dual agonists have been introduced for the clinical treatment of hyperglycaemia and T2DM, which show synergistic and superior metabolic effects compared to single incretin receptor agonists." (PMID 36117625, 2022). "This study demonstrated the importance of combined GLP-1R and GCGR signalling, as administration of the balanced co-agonist to Glp1r-/- mice led to hyperglycaemia, further demonstrating the necessity of GLP-1R and GCGR co-agonism to minimise this predicted side-effect." (PMID 34566894, 2021). "We investigated whether a long-acting glucagon-like peptide-1 receptor agonist, dulaglutide (Dula), safely improved GC-induced hyperglycemia in inpatients, to reduce insulin injection frequency." (PMID 32381085, 2020). "A long-acting glucagon-like peptide 1 receptor agonist dulaglutide could provide glycemic control while reducing the insulin dose and injection frequency in the inpatient care for GC-induced hyperglycemia." (PMID 32381085, 2020). "Several GLP-1R agonist formulations have been introduced for management of hyperglycemia in T2DM." (PMID 31159279, 2019). "Growing evidence suggests that hyperglycemia consistently decreases endogenous GLP-1R levels, which may reduce the efficacy of GLP-1RA therapies." (PMID 30866463, 2019). "Taken together, our findings raise important considerations for incretin-based therapy of stress or infection-induced hyperglycemia and whether those immunoregulatory effects could be related to adverse effects of drugs with GLP-1R activity." (PMID 30800001, 2019). "Therefore, the neuroprotective effects of the GLP-1R agonist exendin-4 (EX-4) against hyperglycemia/lipopolysaccharides (LPS) damage were also evaluated in this study." (PMID 22844396, 2012). "Besides the significant weight loss effect demonstrated by the GLORY-1 study (NCT05607680), mazdutide has been shown to counteract the hyperglycemia induced by GCGR activation by adequately balancing the effects of GLP-1R and GCGR activation, overall reducing HbA1c levels and fasting glucose." (PMID 40004572, 2025). "However, the effects of exercise itself on hyperglycemia-induced endogenous GLP-1R levels in the hypothalamus are unknown." (PMID 30866463, 2019). "As the main objective of our study was to examine the pleiotropic effect of Glp-1R agonism on the healing of gastric ulcer in subjects with hyperglycemia, streptozotocin-induced experimental model was conveniently chosen to represent the physiological conditions of chronic hyperglycemia." (PMID 29095895, 2017). "However, T2DM patients with a lower tolerability for GLP-1R agonists may prefer treatment with DPP-4 inhibitors for the management of hyperglycemia." (PMID 25852463, 2015). "Consequently, GLP-1R mediated improvement of hyperglycaemia could gradually enhance the antidiabetic actions of a dual agonist simultaneously acting via GIP-Rs." (PMID 21935440, 2011). "For GLP-1R, the production of cAMP and activation of PKA are reduced in hyperglycemia, accompanied by induced receptor internalization, thereby impairing its insulinotropic action." (PMID 41236578, 2025). "Sustained hyperglycemia has been shown to downregulate GLP-1R and GIPR expression in pancreatic islets and promotes internalization of GLP-1R via PKA-dependent mechanisms, impairing insulinotropic signaling." (PMID 41236578, 2025).
Hyperglycemia (continued). "Studies indicate that women with PCOS exhibit impaired incretin response, particularly reduced GLP-1 secretion and diminished GLP-1 receptor (GLP-1R) expression in pancreatic β-cells, contributing to insufficient postprandial insulin release and hyperglycemia." (PMID 40076938, 2025). "In this regard, when GLP-1R signalling was abrogated, hyperglycaemic excursions were observed, indicating that GLP-1R activation is essential in offsetting glucagon-induced hyperglycaemia." (PMID 37378828, 2023). "Excellent therapeutic options are Glucagon-like peptide-1 receptor agonists (GLP-1 RAs) and the new GLP1 and gastric inhibitory polypeptide dual receptor antagonists counteract metabolic defects of type 2 diabetes, hyperglycemia and obesity." (PMID 37627585, 2023). "By agonistic action on the glucagon-like peptide-1 receptor (GLP-1R) expressed on β-cells in the pancreas, Ex4 stimulates the secretion of insulin and reverses states of hyperglycaemia." (PMID 37665477, 2023). "Based on their ability to reduce hyperglycemia and body weight, the U.S. food and drug administration (FDA) approved the use of Glucagon-like peptide-1 receptor (GLP-1R) agonists as a treatment for type-2 patients." (PMID 36187092, 2022). "Glucagon-like peptide 1 receptor (GLP-1R) agonists and dipeptidyl peptidase-4 inhibitors (DPP-4i) are approved drugs for the treatment of hyperglycemia in patients with type 2 diabetes (T2D)." (PMID 29466979, 2018). "The glucose-dependent T2D therapies such as glucagon-like peptide-1 receptor (GLP-1R) agonists and dipeptidyl peptidase-4 inhibitors, promote glucose control by minimizing both hyperglycaemia and hypoglycaemia." (PMID 22776039, 2013). "Liraglutide (Lir), a glucagon-like peptide-1 receptor (GLP-1R) agonist, is widely applied to treat T2DM as it can improve hyperglycemia without any risk of hypoglycemia." (PMID 41155741, 2025). "Even though beta cell functionality does not influence exendin uptake, extreme hyperglycaemia can increase it by increasing GLP1R expression." (PMID 38871836, 2024). "Furthermore, GLP-1R agonism can reduce gene transcription of nuclear factor kappa-B (NF-κB) and superoxide dismutase 2 (SOD2) by reversing the hyperglycaemia-induced DNA demethylation." (PMID 39200816, 2024). "It is also necessary to note that, although chronic hyperglycaemia decreases GLP‐1R expression, it does not affect expression of PKA and Epac2 in β‐cells." (PMID 33611845, 2024). "We found that eye drops of exendin-4, a long-acting GLP-1 receptor (GLP-1R) agonist, prevented the increase of L-type Ca2+ current (ILCa) densities of RGCs induced by 4-week hyperglycemia and promoted RGC survival by suppressing L-type VGCC (L-VGCC) activity in streptozotocin-induced diabetic rats." (PMID 37680468, 2023). "In STZ induced hyperglycemic mice model, PGLP-1-VP ameliorates STZ-induced hyperglycemia and improves insulin sensitivity, which indicates that PGLP-1-VP could work as a long-acting GLP-1R agonist in vivo." (PMID 33574570, 2021). "Because other data have suggested that hyperglycemia reduced GLP-1R expression in pancreatic beta cells, GLP-1R expression in tumors may also be decreased in the hyperglycemic state." (PMID 26439622, 2015). "Clinical studies comparing GLP-1R agonists vs. DPP-IV inhibitors revealed that exenatide or liraglutide (GLP-1R agonists currently used in T2D treatment) were more efficient than sitagliptin (a DPP-IV inhibitor) in lowering blood glucose levels, upon hyperglycemia, and body weight in T2D patients." (PMID 25071725, 2014).
Hyperglycemia (continued). "This ‘glucose-regulated’ activity of GLP-1R agonists makes them useful and potentially safer therapeutics for overall glucose control compared to non-regulated therapies; hyperglycaemia can be reduced with minimal hypoglycaemia." (PMID 22776039, 2013). "In the present study, we demonstrate that GLP‐1R expression is improved in β‐cells from diabetic GK rats after RYGB, which significantly increases diabetic β‐cell responsiveness to GLP‐1, thereby enhances efficiency of GLP‐1 on GSIS and ameliorate hyperglycaemia in GK rats." (PMID 33611845, 2024). "A direct comparison of P5 with the reference peptide Ex4 revealed that G-protein signalling downstream of GLP-1R activation in the absence of β-arrestin signalling is sufficient to correct hyperglycaemia, improve insulin sensitivity, preserve pancreatic islet integrity and improve liver steatosis." (PMID 26621478, 2015). "In addition to these findings on atherosclerotic plaque formation, GLP-1R agonists prevented the increase in plasminogen activator inhibitor type-1 (PAI-1) and vascular cell adhesion molecule-1 (VCAM-1) gene expression in response to TNF-α or hyperglycemia in HUVEC through PKA pathway." (PMID 25338737, 2014). "Administration of glucagon to elevate HR in a beta-blocked patient can induce hyperglycemia, and so it should not be overlooked that OXM may have clinical value for these situations as OXM has antidiabetic properties associated with activating the GLP-1R." (PMID 24303183, 2013). "Overall, these data indicate that agonism of GLP-1R or GIPR, individually or in combination, does not affect fatty acids in hepatocytes in response to OA and the combination of OA with palmitic acid or in conditions of hyperglycemia and hyperinsulinemia." (PMID 39607493, 2024).